NRAS (NRAS proto-oncogene, GTPase)
Diseases named in the same sentence as NRAS in open-access papers (continued):
Sharing a sentence is not in itself a finding about the gene and the disease.
cutaneous melanoma (continued). "This phase II study (NCT01693068) aimed to confirm the efficacy and safety of pimasertib at the RP2D in patients with NRAS-mutated cutaneous melanoma, and to compare this with DTIC, the SOC at the time of study initiation." (PMID 32610581, 2020). "Mutations in NRAS account for approximately 28% of cutaneous melanoma, of which more than 80% harbor a glutamine-to-leucine substitution (NRASQ61L), thus compromising the intrinsic GTPase activity of NRAS and increasing its GTP-bound form." (PMID 32517051, 2020). "Further analysis of the 124 BRAF-wild type skin melanomas, we found the NRAS mutation frequency to be 20% (45/227)." (PMID 31848942, 2020). "In cutaneous melanoma, NRAS is mutated in about 15–30% of cases, while KRAS (∼2%) and HRAS (∼1%) play a minor role." (PMID 32850962, 2020). "While BRAF mutations are the most prevalent in cutaneous melanoma, NRAS mutations display more aggressive phenotypes with increased mitotic rate, thicker primary tumors, and poorer prognosis." (PMID 32517051, 2020). "Pimasertib has activity in NRAS-mutated cutaneous melanoma and a safety profile consistent with known toxicities of MEK inhibitors." (PMID 32610581, 2020). "As such, the difference between mucosal and cutaneous melanoma and the mutational landscape of NRAS in sinonasal melanoma is likely more complicated than previously thought." (PMID 32725435, 2020). "MiR-146a acts in the first phases of cancerogenesis in BRAF/NRAS-mutated cutaneous melanoma through NOTCH proteins." (PMID 31683701, 2019). "Although the most frequent types of NRAS mutations are located in codon 61 for both cutaneous melanoma (88%) and mucosal melanoma (54%), mutations at codons 12 and 13 occurred more frequently in mucosal melanomas (46%) than cutaneous melanomas (12%)." (PMID 31398831, 2019). "We show that in addition to being less frequent, BRAF and NRAS mutations are different in mucosal melanoma compared to cutaneous melanomas." (PMID 31398831, 2019). "NRAS mutations on Q61 found in cutaneous melanoma are hence consistent with known mechanisms for UV induction." (PMID 31398831, 2019). "NRAS mutations were targeted to hotspots on codon 61, which is the dominant hotspot in cutaneous melanoma, and codon 12, a hotspot less commonly mutated in cutaneous melanoma." (PMID 31320640, 2019). "We compared those data with NRAS mutations in cutaneous melanomas, hematopoietic and lymphoid tissue malignancies, and thyroid cancers from The Catalog of Somatic Mutations in Cancer (cancer.sanger.ac.uk)." (PMID 31398831, 2019). "Mutations of the oncogenes BRAF and NRAS are the most common genetic alterations in cutaneous melanoma and the prognostic significance of the mutations shows differently." (PMID 31649871, 2019). "Activating hot-spot mutations are mainly found in BRAF (codon V600) and in NRAS (codon Q61, and less frequently in the codons G12 and G13) genes, in 35–50% and 15–25% of cutaneous melanoma, respectively." (PMID 28668077, 2017). "In this work we present an intensively pigmented and well-characterized cell line derived from a highly aggressive NRAS mutated cutaneous melanoma, named MUG-Mel2." (PMID 28522871, 2017). "NRAS was present in 28 of the 105 cutaneous melanomas (27%), and small numbers of KIT and MEK1 mutations were identified in cutaneous melanomas (3 and 4 cases respectively)." (PMID 28228113, 2017). "NRAS mutations occur in ∼20% of human cutaneous melanomas, while HRAS and KRAS mutations are rare in this disease." (PMID 28497782, 2017). "Why KRAS mutations prevail in colorectal, lung and pancreatic cancer, while NRAS or BRAF are mutated more frequently in skin melanoma, and HRAS mutations are predominant in head and neck squamous cell carcinoma is not yet clear." (PMID 28152508, 2017). "NRAS is a frequently UV-mutated oncogene, generally occurring in melanoma of the skin in UV exposed areas, which is proven by characteristic base changes in the DNA (C > T transition)." (PMID 28522871, 2017).
cutaneous melanoma (continued). "Hotspot mutations of the oncogenes BRAF and NRAS are the most common genetic alterations in cutaneous melanoma." (PMID 28797232, 2017). "BRAF mutations were seen in 57% of human cutaneous melanomas and NRAS was mutated in 17% of samples." (PMID 29056717, 2016). "Looking beyond combinations involving mutant EGFR or KRAS, we found that BRAF mutations in skin cutaneous melanoma (SKCM) were negatively associated with NRAS." (PMID 26047463, 2015). "Our panel also included five cutaneous melanoma cell lines wild type for mutations in NRAS, BRAF, GNAQ and GNA11 and only one was highly sensitive to TAK733 with IC50s below 1 nM, while two were considered sensitive with IC50 less than 10 nM." (PMID 22515704, 2012). "Although the overall mutation frequency of KRAS in cutaneous melanoma may be less pronounced than that of BRAF or NRAS, the current findings reinforce the concept that KRAS pathway activation is sufficiently relevant to warrant deeper examination." (PMID 40607411, 2025). "Notably, KIT mutations are usually mutually exclusive of BRAF and NRAS mutations, which are the most common oncogenic drivers in cutaneous melanoma." (PMID 41301010, 2025). "Hyperactivation of the MAPK (mitogen-activated protein kinase) RAF/MEK/ERK signaling pathway is commonly observed in cutaneous melanomas due to NRAS or BRAF mutations, and systemic treatment in these cases may include BRAF and MEK inhibitors." (PMID 37259298, 2023). "NRAS mutations were identified in 28 cutaneous melanoma cases, of which 26 (93%) could be also detected if run on the Idylla system." (PMID 35627184, 2022). "However, the frequency of BRAF and NRAS mutations in acral melanoma is considerably lower than that in cutaneous melanoma, leaving most acral melanoma patients ineligible for treatment with BRAF inhibitors and the combination of BRAF/MEK inhibitors." (PMID 34149718, 2021). "However, such association has also been reported in skin melanomas with NRAS mutation being identified as an independent predictor of disease progression." (PMID 34359736, 2021). "The distribution of BRAF and NRAS mutation varies according to geographic regions, as observed in cutaneous melanoma, and might explain the better survival observed among European patients in comparison with patients from North America and Asia." (PMID 35008570, 2021). "BRAF and NRAS mutation frequencies differ between cutaneous melanoma subtypes." (PMID 34680222, 2021). "In cutaneous melanoma, 21 from 92 patients had NRAS mutations." (PMID 34290710, 2021). "BRAF and NRAS mutations are representative genetic mutations that cause skin melanoma." (PMID 33833342, 2021). "Mutations in BRAF and NRAS are most commonly detected in primary cutaneous melanomas." (PMID 33003469, 2020). "Additionally, these mutations occur independently from mutations of BRAF and NRAS genes, indicating that the pathogenesis of cutaneous melanoma and mucosal melanoma occurs differently." (PMID 31274706, 2020). "BRAF and NRAS mutations occur in approximately 40% and 15–20% of cutaneous melanomas, respectively." (PMID 32610581, 2020). "BRAF and NRAS are common mutation targets in cutaneous melanoma." (PMID 35693877, 2019). "Cutaneous melanoma frequently harbors activating mutations in NRAS (around 20%) or the RAS-regulated kinase BRAF (around 37%), suggesting that the RAS-RAF-MAPK pathway may be critical in the pathogenesis of cutaneous melanoma." (PMID 29349077, 2017). "NRAS mutations are somewhat less frequent in mucosal (10-20%) than cutaneous melanomas (20-30%)." (PMID 28380455, 2017). "Importantly, uveal melanoma shares with cutaneous melanoma the addiction to high levels of ERK activity, but lack NRAS or BRAF mutations that are a hallmark of cutaneous melanoma." (PMID 27034005, 2016). "Notably, common BRAF and NRAS mutations in cutaneous melanoma are associated with increased miR-21 expression." (PMID 26116372, 2015).
cutaneous melanoma (continued). "NRAS mutations are present in 15–30% of melanomas of the skin, with codon 61 most commonly altered." (PMID 24959217, 2014). "Also, the mechanisms of activation of MAPK-pathway in uveal melanoma appear to be distinct from cutaneous melanoma, as mutations in NRAS or BRAF are rarely found." (PMID 23226204, 2012). "Furthermore, in cutaneous melanoma, a correlation of NRAS mutation and higher age was found." (PMID 31500314, 2019). "While BRAF and NRAS mutation are the most two common mutations in cutaneous melanoma, BAP1 mutation frequently occurs in uveal melanomas exclusively with BRAF or NRAS mutations 146, suggesting that BAP1 mutation may be a specific genetic marker for uveal melanoma." (PMID 28544818, 2017). "Conversely, in CoM, the mutational spectrum overlaps with cutaneous melanoma, with frequent alterations in BRAF, NRAS, NF1, and KIT, offering actionable targets for personalised treatment." (PMID 41751395, 2026). "GNAQ and GNA11 mutations are prevalent in primary CNS melanoma but differ from cutaneous melanoma (CM), in which BRAF, NRAS, KIT, and NF-1 mutations are more common." (PMID 41536409, 2025). "The most commonly mutated genes were TERT, BRAF, NRAS, and CDKN2A, consistent with known patterns of mutations in cutaneous melanoma." (PMID 39422848, 2025). "This is in stark contrast to cutaneous melanoma, where B-Raf proto-oncogene, serine/threonine kinase (BRAF) and neuroblastoma RAS viral oncogene homolog (NRAS) mutations predominate." (PMID 40395262, 2025). "In cutaneous melanoma, most commonly driven by BRAF or NRAS mutations, ICIs have demonstrated substantial improvements in overall survival and durable clinical responses." (PMID 41301010, 2025). "NF1 mutations are present in 5% of BRAF-, 13% of NRAS-, and 50% of RASA2-mutant cutaneous melanomas." (PMID 39804140, 2025). "In this study cutaneous melanomas were evaluated to identify the correlation between clinical, histopathological, dermoscopic features, and BRAF, NRAS, and cell cycle genes’ mutational status." (PMID 40867317, 2025). "Novel therapeutic approaches include immunotherapy and targeted therapy (BRAF/MEK or KIT inhibitors), although mutation profiles differ from cutaneous melanoma, with KIT and NRAS mutations more common than BRAF." (PMID 41002705, 2025). "In cutaneous melanoma, activating BRAF mutations (predominantly V600E/K) are commonly reported in approximately 40-56% of contemporary series, and NRAS mutations occur in 15- 30%." (PMID 41384184, 2025). "The reported frequencies of mutations in cutaneous melanoma are 37–60% in BRAF, 13–25% in NRAS, 12% in NF1, 6–7% in MAP2K1, and 2–8% in KIT." (PMID 41295253, 2025). "SF3B1 and KIT have been shown to have a higher mutation rate in MM as compared to cutaneous melanoma, whereas BRAF and NRAS have a lower mutation rate in MM." (PMID 39416390, 2024). "NRAS (breast carcinoma and skin melanoma), CDK4 (NSCLC), and ERBB2 (gastric carcinoma and esophageal carcinoma) were identified as the top identified amplification driver genes in different cancer types." (PMID 38195844, 2024). "In the publicly available GENIE dataset, looking exclusively at cutaneous melanomas shows that the specific mutation rates within primary tumors were 55 % for TERT, 40 % for BRAF, 7.2 % for KIT, 2.5 % for NRAS, and 1.9 % for CDH1." (PMID 38158497, 2024). "We observed that PRSS1 and CTCF mutations in lung adenocarcinomas and skin melanomas show similar resistance-conferring effects to KRAS and NRAS mutations when treated with EGFR and BRAF inhibitors." (PMID 39160568, 2024). "Targetable mutations commonly seen in cutaneous melanoma, such as in the BRAF and NRAS genes, have a lower incidence in mucosal melanoma." (PMID 38778387, 2024).
cutaneous melanoma (continued). "Among the amplification driver genes, NRAS (in breast carcinoma and skin melanoma), ERBB2 (in gastric carcinoma, esophageal carcinoma), and NFATC2 (in ovarian carcinoma and pancreatic carcinoma) were identified in more than one cancer type." (PMID 38195844, 2024). "The rate of NF1 mutations is comparable to that of cutaneous melanoma (~14%); however, BRAF/NRAS mutations rates are remarkably lower, and KIT mutations are observed in at least 13% of cases." (PMID 38201222, 2023). "This panel included cell lines representing all four molecular subtypes of cutaneous melanoma with driver mutations in the BRAF, NRAS, or NF1 genes and a fourth triple wild-type subtype, in which none of these genes are mutated." (PMID 37803324, 2023). "Like in skin melanomas, NF1 mutations can co-exist with either NRAS or BRAF mutations in CMs, albeit infrequently." (PMID 37761808, 2023). "The mutational drivers of cutaneous melanoma change with age - BRAF is the most common driver in the young, while NRAS and other mutations increase in prevalence with increasing age." (PMID 36909026, 2023). "In cutaneous melanoma TERT promoter mutations commonly co-occur (80-90%) with NF1, BRAF or NRAS mutations, and TERT promoter mutations are also found in 15-60% of BRAF/NRAS/NF1 WT cutaneous melanoma background." (PMID 35494035, 2022). "The main genetic drivers for cutaneous melanoma are B-Raf proto-oncogene (BRAF), neurofibromin 1 (NF1), and neuroblastoma RAS viral oncogene homolog (NRAS) mutations, which are primarily mutually exclusive in primary tumours." (PMID 35884596, 2022). "The most common allelic variants (AV) in cutaneous melanoma tissues include BRAF, neuroblastoma RAS viral oncogene homolog (NRAS), mitogen-activated protein kinase kinase 1 (MAP2K1), and proto-oncogene c-KIT (KIT)." (PMID 35205608, 2022). "To assess the efficacy of the ten distinct combinatorial library systems, we first screened the libraries in an NRAS-mutant cutaneous melanoma cell line, IPC298." (PMID 35513429, 2022). "In skin melanoma cell lines, Ganetespid induced downregulation of the MAPK signaling pathway both in BRAF- and NRAS mutated cell lines." (PMID 35326726, 2022). "Driver mutations in choroidal melanomas are mutations in the heterotrimeric G-protein alpha subunits GNAQ and GNA11, while conjunctival melanomas show more resemblance to skin melanoma with oncogenic mutations in BRAF and NRAS." (PMID 35682684, 2022). "Compared to cutaneous melanoma (CM), which mainly harbors BRAF or NRAS mutations, UM predominantly harbors GNAQ or GNA11 mutations." (PMID 35804863, 2022). "Compared with cutaneous melanoma, BRAF mutations were less observed in acral melanoma, while mutant NRAS (26.7%) and Triple-WT (7/15, 46.7%) were more common." (PMID 35688842, 2022). "MAPK signaling is overactive in the majority of CMs, driven by activating mutations in BRAF (~50%) or NRAS (~25%), or loss of function mutations in NF1 (~15%) (Genomic Classification of Cutaneous Melanoma, 2015)." (PMID 35513054, 2022). "Addition of TERT promoter mutation targets in the custom panel was predicted to further increase coverage by ~15% in those cutaneous melanoma patients that are NRAS or BRAF WT." (PMID 35494035, 2022). "We identified no convincing effect of VP in the two CoM cell lines with either a BRAF or NRAS mutation (CRMM1 and CRMM2), whereas the cutaneous melanoma cell line OCM3 did show a response to VP." (PMID 33798262, 2021). "We identified BRAF V600E (11/25; 44%) as the most commonly mutated gene, followed by NRAS (2/25; 8%), and KRAS (1/25; 4%) in cutaneous melanomas." (PMID 34102999, 2021).
cutaneous melanoma (continued). "CoM on the other hand resembles cutaneous melanoma and has driver mutations in BRAF, NRAS, Kit, TERT, or NF1.20–25 Despite their different backgrounds, UM and CoM share the need for the development of new and effective therapies." (PMID 33798262, 2021). "NRAS and BRAF mutations are considered to be somewhat mutually exclusive, with less than 1% of patients with cutaneous melanoma having co-mutations." (PMID 34155457, 2021). "Due to favorable results in phase I trials, pimasertib is the subject of a phase II trial comparing its efficacy to dacarbazine in NRAS-mutant cutaneous melanoma." (PMID 33807778, 2021). "NF-1 has been described as the third most common mutated TSG seen within those who develop cutaneous melanoma, and once more, loss of NF-1 leads to increased signaling within the MAPK and PI3K pathways due to hyperactivation of the NRAS protein." (PMID 34155457, 2021). "RAC1P29S is the third most commonly mutated codon in human cutaneous melanoma, after BRAF V600 and NRAS Q61, and one of the most prominent driver mutations in RAC1 with a frequency of approximately 5% and up to 10% in chronically sun-exposed melanomas." (PMID 34827551, 2021). "Approximately 50% of cutaneous melanoma patients are mutant in BRAF gene, 15–20% of patients are positive for NRAS damaging mutations both leading to a constitutively enhanced MAPK pathway activity." (PMID 34885093, 2021). "Commonly to cutaneous melanoma, mucosal mutations shows alterations in SF3B1, KIT, and NF1 and less frequently mutations in BRAF and NRAS." (PMID 33918490, 2021). "CM shares similarities with both cutaneous melanoma and mucosal melanoma, including their infiltrative nature, their lymphatic and hematogenous spread and the presence of BRAF, NRAS, NF1 and Kit mutations." (PMID 34830847, 2021). "Like cutaneous melanomas, it has been proposed to classify CMs according to their mutational status, resulting in groups of BRAF-mutated, NRAS-mutated, NF1-mutated and triple-wild type (WT) melanomas." (PMID 34830847, 2021). "WES of 103 cutaneous melanomas, including 77 tumor samples and 26 cell lines, found FBXW7 mutations (8.1%) independently of BRAF or NRAS mutation." (PMID 32850962, 2020). "UMs most often have a GNAQ or GNA11 mutation, while cutaneous melanomas usually have a BRAF, NRAS, KIT or NF1 mutation." (PMID 32998469, 2020). "On the other hand, hotspot mutations in the genes BRAF and NRAS, in combination with homozygous deletions of the gene CDKN2A, were frequently found in cutaneous melanoma." (PMID 32825510, 2020). "Following BRAF and NRAS, NF1 is the third gene most commonly mutated in cutaneous melanoma (in about 17% of the cases) and frequently co-occurs with mutations in the RASA2 gene." (PMID 33003469, 2020). "We divide cutaneous melanoma into four subtypes (BRAF-mutant, NF1-deficient, NRAS-mutant and triple wild-type)." (PMID 33585219, 2020). "Another difference with cutaneous melanoma is that the targetable mutations in BRAF and NRAS genes are less prevalent in mucosal melanoma (only 3–15%)." (PMID 33585548, 2020). "The genetic spectrum of conjunctival melanoma, however, includes frequent mutations in the BRAF, NRAS and TERT promoter genes, which are found in cutaneous melanoma as well." (PMID 33396957, 2020). "This panel encompassed two mutually exclusive genetic subsets of cutaneous melanoma, since MeWo and HMCB are BRAF-wt and NRAS mutated (NRAS-m), A375 and SK-MEL-28 are BRAF-m and NRAS wildtype (NRAS-wt)." (PMID 33105692, 2020).